CD36 (CD36 molecule (CD36 blood group))
Diseases named in the same sentence as CD36 in open-access papers (continued):
Sharing a sentence is not in itself a finding about the gene and the disease.
melanoma (continued). "Peroxisome and UGCG functions are required for MAPKi-tolerant CD36+ persister melanoma cells." (PMID 37616051, 2023). "Together, these data are consistent with previous observations that not only BRAFis but also MEKis induce CD36 expression in melanoma cells and that the CD36+ SMC state is an important transitory state leading to the emergence of other MAPKi-tolerant states, which promote resistance." (PMID 37616051, 2023). "Importantly, in our analysis, the expression of peroxisome signature genes and UGCG were positively correlated with CD36 expression in the human melanoma data set of The Cancer Genome Atlas (TCGA)." (PMID 37616051, 2023). "Binding of TSP-1 to CD36 on microvascular endothelium inhibits angiogenesis, but CD36 could induce VM formation in melanoma cells by promoting the adhesion of tumor cells." (PMID 36354702, 2022). "Similar evidence has been provided by other research groups, associating overexpression of CD36 with shorter survival of melanoma patients with tumor-infiltrating CD8+ T cells, while CD36-depleted CD8+ T cells showed greater antitumor potential and survival compared with wild-type CD8+ T cells." (PMID 36203151, 2022). "Together, these findings show that blocking CD36 might be a promising strategy to prevent metastases and relapse in melanoma." (PMID 35406721, 2022). "Of note, CD36 is a useful marker of melanoma cell adaptation, e.g., to MAPK inhibitors." (PMID 35406721, 2022). "In addition to acquiring lipids from adjacent cells, melanoma cells can absorb dietary lipids by expressing high-level CD36, a membrane-bound exogenous lipid deliverer, to facilitate their metastasis." (PMID 36003368, 2022). "Indeed, Treg-specific genetic ablation of CD36 attenuated tumor growth in a mouse model of melanoma and promoted Treg apoptosis while reinforcing CD8 T cell infiltration and effector cytokine production." (PMID 34983949, 2022). "Interestingly, CD36-neutralizing antibody is equally effective on metastatic regression in intravenously-inoculated melanoma, oral carcinoma and mammary gland cancer mouse models." (PMID 35945203, 2022). "Indeed, TAMs from human melanoma and colon cancer tissues as well as from mice bearing 5TGM1, EL4 or B16 melanoma tumors highly express CD36, which leads them to have enhanced lipid uptake compared to naïve macrophages." (PMID 34983949, 2022). "Indeed, intratumoral CD8 T cells from B16 models of melanoma also progressively increase the expression of CD36, possibly as a function adaptation to heightened lipid availability." (PMID 34983949, 2022). "The inhibition of CD36 restricts melanoma metastasis and improves prognosis of melanoma patients." (PMID 36003368, 2022). "Taken together, this study leads us to hypothesize that CD36 expression by melanoma cells modulates the function of integrins to promote shape change and migration on ECM components, thereby facilitating the formation of VM structures." (PMID 34215227, 2021). "Notably, CD36 marks a unique population of this intermediate phenotype, termed the starved-like melanoma cells (SMCs)." (PMID 34604096, 2021). "Accordingly, deletion of CD36 induces high apoptosis combined with a metabolic shift in Tregs, and therefore this leads to a decrease in tumor growth in TregCD36−/− mice engrafted with melanoma." (PMID 34885023, 2021). "Notably, several CD36-blocking agents have been identified and shown anti-tumor activities in different cancer types, including melanoma." (PMID 34604096, 2021). "To further investigate the role of CD36 on VM-competent melanoma cells, we performed inverse invasion assays wherein we tested the ability of C32 melanoma cells (without or with CD36) to crawl through an extracellular matrix (Matrigel) towards a chemoattractant (10% FBS)." (PMID 34215227, 2021). "The aim of the present study is to investigate the currently unknown role of CD36 in VM by melanoma cells." (PMID 34215227, 2021).
melanoma (continued). "Our in-silico analysis of the TCGA database supports our hypothesis that high expression of CD36 correlates with poor outcome for patients with melanoma." (PMID 34215227, 2021). "Clearly, while the refinement of CD36-targeting antibodies requires significant attention, there is increasing interest in CD36 as a potential prognostic for patients with colon, ovarian, breast, small cell lung carcinoma and urinary bladder cancer and melanoma." (PMID 34215227, 2021). "Furthermore, CD36–PPAR-β signaling in melanoma has been shown to modulate mitochondrial fitness and levels of the key metabolite NAD to enable the metabolism of lactic acid to pyruvate." (PMID 34885023, 2021). "CD36-mediated FA uptake is prominent in metastasis-initiating melanoma cells, and this change was correlated with poor prognosis in melanoma patients, thereby highlighting the importance of FA uptake for melanoma progression." (PMID 33121001, 2020). "Recently, the importance of CD36 became apparent, as the blocking of CD36 with neutralizing antibodies resulted in almost complete inhibition of metastasis in human melanoma, breast and oral cancers, demonstrating cancer cells’ reliance on dietary lipids to promote metastasis." (PMID 32731620, 2020). "Furthermore, in melanoma cells, CD36 Thr92 phosphorylation has been shown to reduce the recruitment of Src-family proteins after TSP-1 binding to CD36 and blunt vascular-cell signaling." (PMID 31410189, 2019). "Therefore, QCM is adapted in this proof-of-concept experiment for the analysis of PfEMP1-mediated iRBC binding to the cell surface of CD36-expressing melanoma cells as well as to CSA." (PMID 27296675, 2016). "In addition, transfection of CD36 gene into human Bowes melanoma cells was found to increase the capacity to ingest apoptotic neutrophils, lymphocytes, and fibroblasts, indicating that CD36 may be related to phagocytosis and apoptosis." (PMID 40040886, 2025). "Therefore, our study is highly relevant in understanding this critical question of whether melanoma EV mediates the alteration of CD36 in recipient cells to mediate the development of the premetastatic niche." (PMID 39062552, 2024). "Consequently, blockade of CD36 by genetic ablation or by using neutralizing antibodies reduces FA uptake in tumor cells and dramatically impairs metastasis formation and cancer aggressiveness in a wide variety of cancers including melanoma." (PMID 35912100, 2022). "Thus, the OxLDL/CD36/p38 axis promoted intratumoral CD8+ T-cell dysfunction in the context of melanoma/colorectal carcinoma and may also serve as a therapeutic target in other tumors." (PMID 36131916, 2022). "Tregs were isolated from the SPL, LNs, and tumors of the B16-F10 melanoma–bearing NAC1-KO mice or WT mice, and the expression of CD36 on WT and NAC1-KO iTregs was analyzed at 24 hours, 48 hours, and 72 hours following treatment with 10 mM of LA." (PMID 39773913, 2025). "Our data from melanoma cell line (SKMEL-28 and C32TG)-derived EVs show the upregulation of CD36 when challenged with THP1." (PMID 39062552, 2024). "We used the TIMER-2 gene module to correlate CD36 with the cellular markers and immune infiltrate analysis in TCGA-SKCM melanoma datasets." (PMID 39062552, 2024). "Accordingly, CD36 deletion favors the growth of Lewis lung carcinoma (LL2) and B16F1 melanoma tumor cell implants, while the growth of the same tumors is impaired in syngeneic HRG null mice." (PMID 38469298, 2024). "To verify this, we challenged melanoma-derived EVs to HLEC- and PMA-stimulated THP1 cells, presumably M0 macrophage, and these cells upregulate CD36 after challenging." (PMID 39062552, 2024). "Genetic knockout of CD36 in CD8+ T cells significantly suppresses tumor growth in colorectal cancer and melanoma." (PMID 39402302, 2024). "The use of an anti-CD36-blocking antibody alone restores CD8+ T-cell function and inhibits melanoma growth." (PMID 39402302, 2024).
melanoma (continued). "The CD36+ SMC state is an attractive therapeutic target in melanoma, as it represents a significant subset of drug-tolerant melanoma cells, accounting for approximately 20%–80% of the population persisting from the early MAPKi-response phase to MRD." (PMID 37616051, 2023). "Importantly, as dedifferentiated and NCSC states are also responsible for MAPKi-induced cross-resistance to immunotherapy, targeting these CD36+ cells by dual PEX3+UGCG inhibition could also potentially sensitize melanoma to combined immunotherapy and MAPKis and prevent cross-resistance." (PMID 37616051, 2023). "Having shown that inhibiting peroxisomes and UGCG can induce death of CD36+ MAPKi-tolerant cells, we next interrogated the status of CD36, peroxisomes, and UGCG in melanomas from patients treated with MAPKi." (PMID 37616051, 2023). "Both CD36+ SMC and pigmented melanoma cell states can rely on altered metabolism for their drug tolerance." (PMID 37616051, 2023). "After a 10-day course of treatment, melanomas were collected and analyzed by flow cytometry to confirm that the NNC+PPMP therapy decreased the abundance of CD36+ drug-tolerant cells and reduced AGPS expression." (PMID 37616051, 2023). "In mice models of melanoma, colorectal cancer, and pancreatic ductal adenocarcinoma (PDAC), CD8+ TILs have been reported to upregulate CD36 expression in order to facilitate extracellular lipid uptake." (PMID 37700339, 2023). "Once infiltrated in tumors (i.e., NSCLC, melanoma and colon carcinoma), Tregs adapt to the TME’s nutrient availability, by shifting their metabolism from DNL to CD36-mediated FA uptake." (PMID 35945203, 2022). "Treg cells from non-small-cell lung carcinoma, melanoma and CRC display increased FA uptake, high lipid content and CD36 upregulation compared with Tregs from other tissues." (PMID 36568966, 2022). "In melanoma, the starved melanoma cell (SMC) state found early in minimal residual disease (MRD) is characterized by high expression of CD36." (PMID 35406721, 2022). "In a mouse melanoma model, TAMs take up oxidized LDL through the scavenger receptor CD36, contributing to protumor function." (PMID 34677277, 2021). "Further supporting a key role for FAO during drug tolerance, CD36, a key lipid transporter and biomarker of the SMC state, was among the most significantly upregulated proteins on the surface of melanoma cells following short-term treatment with MAPKi." (PMID 34830962, 2021). "Gene expression of CD36, MARCO, and various FABP isoforms in 355 patients (208 patients with melanoma versus 147 healthy skin controls) was analyzed, according to the transcriptome expression data reported in the IST Online database." (PMID 32209538, 2020). "The expression of CD36, MARCO, FABP4, FABP6, and FABP7 in melanoma samples and healthy skin biopsies is visualized, according to data retrieved from the IST Online database." (PMID 32209538, 2020). "CD36 Thr92 phosphorylation in melanoma cells is induced by phorbol-12-myristate-13-acetate (PMA) during protein synthesis and transport through the Golgi 61, and CD36 Ser237 phosphorylation inhibits FA uptake by platelets and intestinal cells." (PMID 31410189, 2019). "Isolated cell membranes of melanoma cells were immobilized to the quartz surface via PLL and were stained with an anti-CD36 antibody." (PMID 27296675, 2016). "We detected the internalized EVs with CD36 in the THP1 cells, demonstrating that melanoma EVs could be important factors in upregulating CD36 in monocytic cells." (PMID 39062552, 2024). "These cues encourage us to examine the expression of CD36 and other immunosuppressive markers in histopathological slides of LN tissue from four melanoma patients and two normal LN from non-cancerous individuals." (PMID 39062552, 2024). "Under basal conditions in melanoma cells, CD36 is predominantly non-phosphorylated and presumed to be active." (PMID 37371076, 2023).
melanoma (continued). "In Cd36−/− mice receiving different cancer cell implants (murine Lewis lung carcinoma LCC cells, murine B16F10 melanoma cells, Hepa1-6 hepatoma cells, CT26 or MCA-38 colon cancer cells) tumor growth is reduced, and the number of metastases is decreased compared to WT mice." (PMID 36568966, 2022). "Hence, when specific CD36 knock-down in CD8+ T cells is combined to anti-PD-1 antibodies, the T cell antitumor response is drastically improved, as well as survival of melanoma-bearing mice." (PMID 35945203, 2022). "Further investigation revealed a role for laminin, but not collagen or fibronectin, as ligands for CD36 expressing melanoma cells." (PMID 34215227, 2021). "Transient knockdown of CD36 in melanoma cells did not influence cell viability but did compromise the number of cells that migrated, again suggesting a role for CD36 in cell adhesion." (PMID 34215227, 2021). "However, fatty acid transporters such as CD36 and FABP4 were upregulated in metastatic melanoma compared to primary melanoma, suggesting increased fatty acid uptake activity." (PMID 37849907, 2021). "TSP-1 secreting LL2 cells were sensitive to loss of CD36 or HRG, while TSP-1 negative B16F1 melanoma cells were not sensitive unless they were stably transfected with a TSR-expressing plasmid." (PMID 22808089, 2012). "Three different DC lines cultured for 7–9 days in medium containing GM-CSF and IL-4 (CD14−, CD36+ and CD83−) showed higher levels of intracellular MC1R than short time cultured monocytes, comparable to that observed in the low MC1R expressing BL melanoma cell line." (PMID 12177778, 2002). "While the role of CD36 in this setting remains unclear, the level of CD36 cell surface expression remained stable in MAPK inhibitor-resistant cells and offers the possibility to serve as a potential biomarker for this drug resistant population in melanoma." (PMID 37371076, 2023). "Our own interrogation of the TCGA-SKCM database suggests that high expression of CD36 correlates with poor clinical outcome for patients with melanoma (albeit not significantly) and corroborates the study by Nath and Chan; thus lending further weight to investigating CD36 in melanoma." (PMID 34215227, 2021). "To understand the role of CD36 in melanoma, we first analyzed the SKCM dataset for clinical prognosis, evaluated the percentage of CD36 in lymphatic fluid-derived EVs (LEVs), and tested whether melanoma-derived EVs increase CD36 expression and induce M2-macrophage-like characteristics." (PMID 39062552, 2024). "Furthermore, CD36 and CD83 expressions were detected in human melanoma cells, but we were not able to confirm it in our studies." (PMID 34885093, 2021).
type 2 diabetes (69 papers, 2010 to 2025). "In the CAD group, we demonstrated that the rs3173798 polymorphism of the CD36 gene is associated with cardiovascular risk factors such as type 2 diabetes, high hsCRP, body mass index, and younger age at myocardial infarction." (PMID 40565598, 2025). "In the type 2 diabetes group, associations between CD36 gene polymorphisms and CD36 gene methylation were noted." (PMID 36031603, 2022). "We aimed to determine the effects of CD36 gene polymorphisms and hypermethylation on the plasma CD36 protein levels in type 2 diabetes." (PMID 36031603, 2022). "Another case–control study on 61 CD36-deficient patients and 25 controls showed that the patients were likely to have a higher type 2 diabetes prevalence, fasting glucose, glycated hemoglobin and HDL-cholesterol, and likely to have a lower triglyceride value." (PMID 23249574, 2012). "Among another French family study, a rare nonsense mutation (1079 T > G) in CD36 locus showed linkage with familial type 2 diabetes risk." (PMID 23249574, 2012). "Previously, our genome-wide PrediXcan analysis (GWA) of data from Vanderbilt BioVu patient biobank associated low CD36 expression in muscle/heart, and a SNP (rs17236824) close to the transcription start site, with renal, ophthalmic and neurological complications of type 2 diabetes." (PMID 39503770, 2025). "Combined with our results, it can be inferred that high level of CD36 expression in muscle may be associated with the incidence of type 2 diabetes, and IR of the LBW infants with high-fat diets." (PMID 34983495, 2022). "The aim of this study was to determine whether plasma concentrations of sCD36 (soluble CD36) are associated with the presence of type 1 or type 2 diabetes." (PMID 31109109, 2019). "CD36 has been reported to be associated with type 2 diabetes (T2D)." (PMID 31109109, 2019). "Moreover, as we have previously observed, LCFA uptake and lipid deposition in the liver are directly related to CD36 expression, suggesting a causative role for increased CD36 expression in the pathogenesis of type 2 diabetes." (PMID 24751397, 2014). "Among a cohort composed of 675 obese adults (age >40 yrs and body mass index >25) in the Netherlands, rs1527479, a C/T SNP in the upstream promoter region in the CD36 gene, homozygous carrier was associated with prevalent type 2 diabetes, and more so in women and high BMI (>27) group." (PMID 23249574, 2012). "Besides endogenous ligands such as oxLDL, exogenous PPAR-γ ligands, including the thioglitazone class of drugs, also upregulate CD36, perhaps contributing to the increase in cardiovascular risk associated with their use in patients with type 2 diabetes." (PMID 35438721, 2022). "We used PrediXcan again to query whether low expression levels of CD36 mRNA in blood or arteries associate with type 2 diabetes complications and found strong associations between low vascular CD36 and renal, ophthalmic and neurological manifestations of type 2 diabetes." (PMID 39503770, 2025). "Type 2 diabetes increased cardiac CD36 S-acylation, CD36 sarcolemmal localisation, FA oxidation rates and triglyceride storage in the diabetic heart." (PMID 40357580, 2025). "In type 2 diabetes mice, a specific Cd36+ cluster (cluster 18, monocytes/macrophages 2) was identified as the precursor of osteoclasts with diminished differentiation potential." (PMID 39281831, 2024). "The role of CD36 in the regulation of mitochondrial function in the treatment of IR and type 2 diabetes needs to be determined." (PMID 36979708, 2023). "Despite the controversy regarding IR, CD36 emerges as a biomarker for patients with type 2 diabetes and related complications." (PMID 36979708, 2023). "The evaluation of the effects of genetic and epigenetic variability on the expression of the CD36 gene and therefore on sCD36 during type 2 diabetes seems interesting." (PMID 36031603, 2022).